JPX (JPX transcript, XIST activator)
Synonyms: ENOX; LINC00183; DCBALD06; NCRNA00183
Gene: Long non-coding RNA gene on chromosome X (73,943,934 to 74,070,423, forward strand). Ensembl gene ENSG00000225470.
Gene Ontology:
Biological process: positive regulation of gene expression; SRP-dependent cotranslational protein targeting to membrane, signal sequence recognition
Cellular component: signal recognition particle, endoplasmic reticulum targeting
Diseases named in the same sentence as JPX in open-access papers:
JPX is named in the same sentence as 30 diseases in open-access papers, as found by Europe PMC text mining. Sharing a sentence is not in itself a finding about the gene and the disease. The quoted sentences say what the papers report.
lung carcinoma (23 papers, 2020 to 2025). "We combined an lncRNA microarray and bioinformatic prediction to screen out lncRNA JPX, which has potential binding sites with miR-33a-5p and is associated with lung cancer tumorigenesis." (PMID 31941509, 2020). "In our study, we found for the first time that JPX was highly expressed in lung cancer patients and was significantly linked to tumor size and TNM stage." (PMID 31941509, 2020). "For example, in lung cancer, JPX/miR-33a-5p/Twist1 regulatory axis promotes the occurrence and metastasis of lung cancer by activating Wnt/β-catenin signaling pathway." (PMID 38811958, 2024). "In lung cancer, JPX was reported to be upregulated in three experiments, where its expression was correlated with clinical characteristics, such as tumor size, stage, and poor survival." (PMID 38672608, 2024). "Another study demonstrated that the upregulated lncRNA JPX promoted lung cancer proliferation and metastasis by the JPX/miR-33a-5p/Twist1 axis activating Wnt/β-catenin signaling both in vitro and in vivo." (PMID 38262966, 2024). "Melatonin downregulates the lncRNA just proximal to XIST (JPX), which is overexpressed in lung cancer tissues." (PMID 37190145, 2023). "For example, the lncRNA JPX transcript, XIST activator (JPX) was shown to upregulate the Twist1 expression by sponging miRNA-33a-5p to regulate the growth and metastasis of lung cancer." (PMID 35800083, 2022). "JPX regulated tumorigenesis and metastasis via JPX/miR-33a-5p/Twist1 axis and activated Wnt/β-catenin signaling in lung cancer." (PMID 36494339, 2022). "It has been found that lncRNA JPX promoted the metastasis of lung cancer via sponging the miR-33a-5p, up-regulated Twist1 expression, led to activating Wnt/β-catenin signaling." (PMID 35860557, 2022). "As reported, JPX has a pivotal function in the development of several cancers, such as colorectal, gastric, cervical, and lung cancers." (PMID 36620545, 2022). "A long non-coding RNA, JPX, and Twist1 transcription factor are up-regulated in lung cancer and induce EMT via inhibition of miR-33a-5p and activation of Wnt/β-catenin signaling." (PMID 34660694, 2021). "For example, lncRNA JPX is upregulated in metastatic lung cancer and shows the capacity to promote lung cancer growth and metastasis." (PMID 33618674, 2021). "The lncRNA JPX was highly expressed in lung cancer metastatic tissues and was positively correlated with tumor size and tumor stage." (PMID 34745940, 2021). "JPX promoted lung cancer cell growth and invasion via the JPX/miR-33a-5p/Twist1 axis and by activating Wnt/β-catenin signaling." (PMID 34745940, 2021). "A recent study proved that lncRNA JPX promotes lung cancer progression via modulating miR-33a-5p/TWIST1 axis." (PMID 34224315, 2021). "The results indicate that the JPX/miR-33a-5p/Twist1 axis regulates lung carcinoma by activating Wnt/β-catenin signaling, suggesting a therapeutic potential for lung cancer treatment." (PMID 31941509, 2020). "Overall, these results indicated that JPX overexpression promoted the lung cancer cell growth and proliferation in vitro and facilitated the lung tumor growth in xenograft mouse model." (PMID 31941509, 2020). "To further confirm the interaction between JPX and miR-33a-5p, we firstly identified the subcellular location of JPX in lung cancer cells." (PMID 31941509, 2020). "We observed that lncRNA JPX was upregulated in lung cancer metastatic tissues and was closely correlated with tumor size and an advanced stage." (PMID 31941509, 2020). "Although we have not tested the function of JPX in lung cancer stem cells at present, our results provide a deeper understanding of the role of JPX in lung cancer cells as well as a new direction for future research." (PMID 31941509, 2020). "It has been reported that lncRNA JPX/miR-33a-5p/Twist1 axis regulates tumorigenesis and metastasis of lung cancer by activating Wnt/β-catenin signaling." (PMID 32943989, 2020).
lung carcinoma (continued). "The present work demonstrated that lncRNA JPX, miRNA-33a-5p, and Twist1 constituted a ceRNA network to regulate lung cancer growth and metastasis." (PMID 31941509, 2020). "Subcutaneous tumor formation experiments revealed that JPX overexpression significantly promoted the formation of subcutaneous tumors of lung cancer cells, while miR-33a-5p overexpression abrogated the JPX-enhanced tumorigenicity in vivo." (PMID 31941509, 2020). "Pearson’s correlation analysis showed that the JPX expression was positively correlated with Twist1 in lung cancer patients." (PMID 31941509, 2020). "Functionally, JPX promoted lung cancer cell proliferation in vitro and facilitated lung tumor growth in vivo." (PMID 31941509, 2020). "In the present study, we identified that JPX, an upregulated lncRNA in lung cancer, acted as a ceRNA for Twist1 through binding with miR-33a-5p." (PMID 31941509, 2020). "Since studies have shown that miR-33a-5p negatively regulates its target gene, Twist1, we aimed to further investigate the relationship between JPX and Twist1 in lung cancer." (PMID 31941509, 2020). "Correlation regression analysis showed that the high JPX expression in 116 lung cancer patients was closely related to large tumor size (P = 0.0009) and the advanced TNM stage (P = 0.0003)." (PMID 31941509, 2020). "Nuclear-cytoplasmic fractionation showed that JPX was mainly located in the cytoplasm of lung cancer cells." (PMID 31941509, 2020). "RT-qPCR and western blotting were conducted to detect the expression levels of lncRNA JPX and Twist1 in lung cancer cell lines and tissues." (PMID 31941509, 2020). "In this work, we discovered a novel ceRNET driven by JPX and involving miR-378a-3p and its different mRNAs targets, eliciting shared oncogenic pathways, thus consistently and ultimately refining the oncogenic role of JPX in lung cancer, particularly in LUAD, the most common subtype of NSCLC." (PMID 38672608, 2024). "Taken together, the data indicate that JPX expression is markedly increased in tumor tissues, which is consistent with data that have already reported on smaller patient cohorts, suggesting an oncogenic role of JPX in lung cancer." (PMID 38672608, 2024). "Overall, the data unveil a novel ceRNET (competing endogenous RNA network), wherein JPX acts as a ceRNA by binding to miR-378a-3p, thus reducing the miRNA silencing activity toward its downstream targets, and eliciting oncogenic pathways driving lung cancer." (PMID 38672608, 2024). "JPX enhances the proliferation of lung cancer cells by sponging miR-362-3p." (PMID 37190145, 2023). "Hence, melatonin has antiproliferation potential for lung cancer by regulating the JPX–miR-362-3p axis." (PMID 37190145, 2023). "LncRNA JPX was identified as an oncogenic regulator in lung cancer." (PMID 35681693, 2022). "Collectively, the data indicated that JPX and Twist1 were coordinately upregulated in lung cancer." (PMID 31941509, 2020). "Interestingly, JPX expression was higher in patients with advanced lung cancer than in those with early lung cancer." (PMID 31941509, 2020). "In this study, we showed that JPX was significantly upregulated in lung cancer tissues and cells." (PMID 31941509, 2020). "Twist1 was highly expressed in lung cancer cells, which was consistent with JPX expression." (PMID 31941509, 2020). "On the one hand, JPX acts as an oncogene to promote the development of ovarian and lung cancer." (PMID 31941509, 2020). "In addition, it has been reported that the aberrant expression of lncRNA JPX is related with the development of hepatocellular carcinoma and lung cancer." (PMID 32943989, 2020). "In addition, miR-33a-5p was upregulated when the lung cancer cells were transfected with JPX siRNA s." (PMID 31941509, 2020). "Taken together, the data suggested that JPX acted as a sponge for miR-33a-5p in lung cancer cells." (PMID 31941509, 2020).
lung carcinoma (continued). "Additionally, Twist1,a target of miR-33a-5p, was found to be coordinately upregulated with JPX in lung cancer." (PMID 31941509, 2020). "The results indicate that JPX plays an oncogenic role in lung cancer." (PMID 31941509, 2020). "Although JPX is confirmed to involve in lung cancer, colorectal, hepatocellular and ovarian cancer, the expression, functional importance and mechanism of action of lncRNA JPX in CC remain unknown." (PMID 32943989, 2020). "However, whether Twist1 participates in the Wnt/β-catenin pathway directly or indirectly, and whether JPX affects Twist1 expression or regulates other pathways through RNA-binding proteins to promote lung cancer development remain unclear." (PMID 31941509, 2020). "Importantly, JPX promoted lung cancer malignant processes and tumor growth in vivo." (PMID 31941509, 2020). "However, JPX was downregulated when the lung cancer cells were transfected with miR-33a-5p mimics." (PMID 31941509, 2020). "Interestingly, JPX and Twist1 were coordinately upregulated in lung cancer tissues and cells." (PMID 31941509, 2020). "Importantly, JPX overexpression could restore the miR-33a-5p-induced abnormal expression of EMT- and Wnt/β-catenin pathway-associated proteins in lung cancer cells." (PMID 31941509, 2020). "In order to verify whether miR-33a-5p could inhibit lung cancer cell growth and metastasis in vivo and whether JPX could reverse miR-33a-5p-induced suppression of the malignant process of lung cancer cells, co-expression of miR-33a-5p and JPX in nude mice was conducted by intravenous injection." (PMID 31941509, 2020). "In addition, to further prove that JPX could upregulate β-catenin expression, we transfected siRNAs of CTNNB1, which is a gene encoding β-catenin, in lung cancer cells." (PMID 31941509, 2020). "A recent study also reported several abnormal expressed lncRNAs in lung cancer, such as lncRNA-XIST and JPX." (PMID 35651789, 2022). "In lung cancer, lncRNA JPX was reported to upregulate Twist1 by competitively sponging miR-33a-5p, subsequently inducing EMT and lung cancer cell invasion." (PMID 35568824, 2022). "Studies have shown that miR-33a-5p can activate Wnt/β-catenin signals through the JPX/Twist1 axis to participate in the EMT process, making lung cancer cells easy to metastasize." (PMID 35646118, 2022). "Although several lncRNAs such as JPX, UCA1, and JHDM1D-AS1 have been reported to coordinate lung cancer progression, most aberrantly expressed lncRNAs in lung cancer remain uncharacterized." (PMID 33618674, 2021). "Three differentially expressed lncRNAs listed in the CDEGs, namely, ILF3-AS1, JPX, and RPPH1, have already been reported to be involved in the progression of lung cancer by affecting cell proliferation and migration." (PMID 34336829, 2021). "Next, we measured JPX expression in human normal lung bronchial epithelial cells (BEAS-2B) and four lung cancer cell lines (SPC-A-1, LTEP-a-2, A549, NCI-H1299) by RT-qPCR." (PMID 31941509, 2020). "To confirm JPX expression in lung cancer tissues, we performed RT-qPCR to detect JPX in 116 pairs of lung cancer tissues and adjacent noncancerous tissues and found significantly higher JPX expression in lung cancer tissues than in adjacent normal tissues." (PMID 31941509, 2020). "Additionally, JPX upregulated Twist1 by competitively sponging miR-33a-5p and subsequently induced EMT and lung cancer cell invasion." (PMID 31941509, 2020). "Together, the results suggested that JPX was aberrantly upregulated in lung cancer tissues and cells and was closely correlated with tumor size and TNM stage, suggesting an oncogenic role of JPX in lung cancer." (PMID 31941509, 2020). "In the current study, we found that JPX could increase Twist1 expression by adsorbing miR-33a-5p, thereby activating Wnt/β-catenin signaling pathway to promote EMT progression in lung cancer cells." (PMID 31941509, 2020).
lung carcinoma (continued). "Further assays revealed that JPX participated in the activation of Wnt/β-catenin signaling by regulating miR-33a-5p/Twist1, which in turn promoted the EMT process, ultimately influencing the of lung cancer process." (PMID 31941509, 2020). "As an oncogene, JPX affected the tumor size, TNM staging, and metastasis of lung cancer." (PMID 31941509, 2020). "Interestingly, Pearson correlation analysis showed a negative correlation between the expression level of JPX and miR-33a-5p in lung cancer tissues." (PMID 31941509, 2020). "In summary, our results demonstrate that the lncRNA JPX/miRNA-33a-5p/Twist1 axis may act as a new ceRNA regulatory network, participating in the EMT process by activating the Wnt/β-catenin signaling pathway, thus accelerating the malignant processes of lung cancer." (PMID 31941509, 2020).
cervical cancer (5 papers, 2020 to 2025). A primary or metastatic malignant neoplasm involving the cervix. "Among them, lncRNA JPX, a known oncogene, promotes the progression of gastric cancer, cervical cancer and non-small cell lung cancer." (PMID 38784043, 2024). "LncRNA JPX can promote cervical cancer progression by regulating the miR-25–3p/SOX4 axis." (PMID 34026852, 2021). "Furthermore, combining lncRNA microarray and bioinformatic prediction, we also found that there were binding sites with miR-25-3p in JPX, and the expression of JPX was negatively correlated with miR-25-3p in cervical cancer tissues." (PMID 32943989, 2020). "Our study demonstrates that JPX promotes cervical cancer progression through modulating the miR-25-3p/SOX4 axis, and may serve as a potential target for CC therapy." (PMID 32943989, 2020). "JPX regulated GC development through miR-197/CXCR6 axis and yet related with non-small cell lung cancer and cervical cancer." (PMID 36567977, 2022).
ovarian carcinoma (4 papers, 2020 to 2024). A malignant neoplasm originating from the surface ovarian epithelium. "To determine whether XIST, JPX, and FTX downregulation could be caused by chromosomal deletions, we also examined Copy Number Variation (CNV) across ovarian cancer grades." (PMID 39546568, 2024). "In addition, highly expressed JPX shows poor prognosis; promotes the proliferation, invasion, and migration of human ovarian cancer cells, and inhibits cell apoptosis by activating the PI3K/Akt/mTOR signaling." (PMID 31941509, 2020). "JPX was reported to act as an oncogene in ovarian cancer and non-small-cell lung cancer by promoting cell proliferation, invasion, and migration." (PMID 33261009, 2020).
hepatocellular carcinoma (3 papers, 2020 to 2022). A malignant tumor that arises from hepatocytes. "A previous study showed downregulation of JPX was associated with the poor prognosis and overall survival of hepatocellular carcinoma." (PMID 35681693, 2022). "Recent study has shown that exosomal JPX from hepatocellular carcinoma (HCC) cells promotes XIST expression by inhibiting the function of CCCTC-binding factor (CTCF) in blood cells." (PMID 31941509, 2020). "In hepatocellular carcinoma, JPX-dependent induction of XIST suppresses hepatocellular carcinoma progression by binding to the miR-155-5p oncomiR." (PMID 33261009, 2020).
non-small cell lung carcinoma (3 papers, 2020 to 2022). A group of at least three distinct histological types of lung cancer, including non-small cell squamous cell carcinoma, adenocarcinoma, and large cell carcinoma. "Here, for the first time, our study showed that the expression levels of JPX were markedly increased in CC tissue samples and cell lines in comparison to that in normal tissue samples and cells, consistent with the report that JPX was increased in non-small-cell lung cancer." (PMID 32943989, 2020).
breast carcinoma (2 papers, 2016 to 2020). "The TF MEF2C interacts with the lncRNA JPX, miR-193a/b, miR-145, and miR-197, and every transcript in these structures is associated with breast cancer, suggesting they may play critical roles in tumorigenesis in combination with an L-FFL motif." (PMID 27322142, 2016). "SNHG5 and JPX ranked 6th and 7th by CLING, are implicated in gastric cancer and breast cancer, respectively." (PMID 32211391, 2020). "As another example, the lncRNA JPX is an Xist activator, yet Xist expression is downregulated in breast cancer." (PMID 27322142, 2016).
esophageal squamous cell carcinoma (2 papers, 2022 to 2024). Esophageal squamous cell carcinoma (ESCC) is a type of esophageal carcinoma (EC) that can affect any part of the esophagus, but is usually located in the upper or middle third. "However, the function of JPX in the progression of esophageal squamous cell carcinoma (ESCC) remains unclear." (PMID 35681693, 2022).
atherosclerosis (1 paper, 2024). A disease characterized by the build-up of fatty material and calcium deposition in the arterial wall resulting in partial or complete occlusion of the arterial lumen. "The LncRNA JPX expression is upregulated in senescent VSMCs and atherosclerotic arteries, and the JPX-enriched chromatin microenvironment mediates VSMC senescence and promotes atherosclerosis." (PMID 39595622, 2024).
bladder cancer (1 paper, 2016). "Also, the MEF2C, miR-145 and JPX correlated with the survival of bladder cancer patients (P=0.026)." (PMID 27322142, 2016).
endometrial cancer (1 paper, 2024). Primary or metastatic malignant neoplasm involving the endometrium (mucous membrane that lines the endometrial cavity). "In Ishikawa and JEC endometrial cancer cell lines, we used siRNA-mediated suppression of JPX to find lower cell viability, increased apoptosis, cell cycle arrest, and reduced migration and invasion." (PMID 38784043, 2024).
esophageal cancer (1 paper, 2022). A primary or metastatic malignant neoplasm involving the esophagus. "The results showed that downregulation of JPX significantly suppressed the migration and invasion of esophageal cancer cells, whereas overexpression of JPX led to a significant increase in esophageal cancer cell migration and invasion." (PMID 35681693, 2022). "Cotransfection of JPX and miR-516b-5p abolished JPX-promoted cell tube length in HUVECs from the esophageal cancer cells conditioned medium in EC9706 cells." (PMID 35681693, 2022). "The results showed that the expression levels of JPX were significantly highly expressed in esophageal cancer cells, including EC9706, Eca109, and KYSE150, compared with those in normal esophageal epithelial cell line, Het-1A." (PMID 35681693, 2022). "We then investigated JPX expression in four esophageal cancer cell lines and a normal esophageal epithelial cell line." (PMID 35681693, 2022).
glioblastoma multiforme (1 paper, 2022). "Similarly, lncRNA JPX facilitated aerobic glycolysis through the FTO/PDK1 axis, thus conferring resistance to temozolomide in glioblastoma multiforme (GBM) cells." (PMID 35843942, 2022).
glioma (1 paper, 2017). A benign or malignant brain and spinal cord tumor that arises from glial cells (astrocytes, oligodendrocytes, ependymal cells). "Among differentially expressed lncRNAs, we further validated seven lncRNAs (7SL, EGO-A, HOTAIR, JPX, MEG3, RNCR3, and ZFAS1) on a bigger cohort of glioma samples of different WHO malignancy grades and histopathological subtypes." (PMID 29138748, 2017).